U3 (Small nucleolar RNA U3 )
Synonyms: LOC124904666
Gene: Small nucleolar RNA gene on chromosome 1 (218,541,690 to 218,541,899, reverse strand). Ensembl gene ENSG00000212610.
Gene Ontology:
Biological process: RNA processing
Cellular component: nucleolus
Homologues: Orthologues: chimpanzee U3 (99% identical), macaque U3 (90% identical). Paralogues in human: U3 (81% identical), SNORD3G (80% identical), SNORD3P1 (79% identical), U3 (79% identical), U3 (77% identical), U3 (76% identical), SNORD3E (76% identical), U3 (75% identical), U3 (74% identical), SNORD3D (73% identical), U3 (73% identical), U3 (72% identical), and 14 more.